FRMD6 (FERM domain containing 6)
Diseases named in the same sentence as FRMD6 in open-access papers (continued):
Sharing a sentence is not in itself a finding about the gene and the disease.
tumor (14 papers, 2016 to 2025). "Both RASSF1A and FRMD6 act as tumor suppressors by binding to MST kinase and activating the Hippo pathway, ultimately reducing YAP activity, a key driver of tumorigenesis." (PMID 38926528, 2024). "FRMD6, on the other hand, induces senescence, a state of cell cycle arrest that hinders tumor cell proliferation." (PMID 38926528, 2024). "As for the mechanisms of these functions, we found that HNRNPA2B1 downregulated FRMD6, a tumor suppressor, by accelerating the maturation of miR-93-5p in an m6A-dependent manner." (PMID 37215455, 2023). "Altogether, these results not only validate the positive hit selection from our screen but also uncover tumor-suppressive functions for both Salvador and FRMD6 in TNBC, through inhibition of the YAP oncogene." (PMID 34031411, 2021). "In particular, we found the tumor-suppressive action of two Hippo members, Salvador and FRMD6, to be mediated through inhibition of the oncogene YAP and discovered a therapeutic application in targeting YAP in TNBC." (PMID 34031411, 2021). "The function of FRMD6 has, therefore, been mainly investigated in the context of cell proliferation or tumor suppression." (PMID 32200438, 2020). "Merlin, a tumor suppressor, is known to promote the Hippo pathway activation whereas the effect of FRMD6 on the pathway remains controversial." (PMID 27661120, 2016). "To examine whether FRMD6 functioned as a tumor inhibiting factor in PCa cells, we constructed FRMD6-overexpressing DU145 and PC3 cell lines." (PMID 37215455, 2023). "Given its putative tumor suppressor properties, FRMD6 may play a crucial role in mediating the role of 1,25D in inhibiting proliferation of immune cells." (PMID 27454520, 2016). "In addition, we examined activity of Erk and ATK kinases and c-Met RTK on the GBM tumor sections derived from the GBM tumors with high or low FRMD6 levels by immunohistochemistry (IHC)." (PMID 27661120, 2016). "Expression of CDX2 is higher in epithelial-like tumor (CMS2/3), while expression of HTR2B and FRMD6 is higher in mesenchymal-like tumor (CMS4)." (PMID 37404825, 2023). "We also show that activation of the Hippo pathway blocks tumor growth through inhibition of the oncoprotein YAP and uncover tumor regulatory functions for Hippo pathway members (SAV1 and FRMD6)." (PMID 34031411, 2021).
infection (2 papers, 2024 to 2025). The state of being infected such as from the introduction of a foreign agent such as serum, vaccine, antigenic substance or organism. "For example, we observe significant HCMV-induced loss of TEAD1 binding, chromatin accessibility, and H3K27ac levels proximal to the promoters of the Hippo pathway genes FRMD6 and RASSF2, both of which have significantly diminished gene expression subsequent to infection (see next section)." (PMID 40928347, 2025). "Notably, even under confluent conditions, Ad-FRMD6 infection resulted in increased levels of p21, p16, and pYAP/YAP compared to control cells, suggesting that FRMD6 functions similarly in both semi-confluent and confluent conditions." (PMID 38926528, 2024).
FRMD6 also shares sentences with these, for which no sentence is quoted: hepatocellular carcinoma (2 papers); melanoma (2); cervical squamous cell carcinoma (1); Cognitive impairment (1); epilepsy (1); Hyperkeratosis (1); leukemia (1); pituitary tumor (1).